OSM (oncostatin M)
Diseases named in the same sentence as OSM in open-access papers (continued):
Sharing a sentence is not in itself a finding about the gene and the disease.
psoriasis (25 papers, 2014 to 2025). An autoimmune condition characterized by red, well-delineated plaques with silvery scales that are usually on the extensor surfaces and scalp. "Tumor necrosis factor-alpha (TNF-α), interleukin-1 alpha (IL-1α), interleukin-17A (IL-17A), interleukin-22 (IL-22), and oncostatin M (OSM) are closely associated with the pathogenesis of psoriasis." (PMID 36999136, 2023). "Oncostatin M (OSM), a member of the IL-6 family of cytokines, has been linked to inflammatory barrier tissue diseases including psoriasis, atopic dermatitis, IBD, and allergic airway disease but has no defined role in host defense." (PMID 36591258, 2022). "In human skin cultures, chemerin is significantly downregulated by IL-17 and IL-22, key cytokines implicated in psoriasis, whereas it is upregulated by acute phase cytokines oncostatin M and IL-1β." (PMID 25659101, 2015). "To confirm the results obtained by RNA‐seq, we performed qPCR to detect and quantify CXCL1, CXCL2, CXCL8, CSFR3, OSM and TREM1, in addition to the psoriasis‐associated genes IL‐17A and IL‐23." (PMID 40181552, 2025). "We further showed induction of CXCL12 in HMEC-1 cells by either mixture of pro-inflammatory cytokines (IL-17A, IL-22, TNF, IL-1α, and oncostatin M), or serum from active psoriasis patients." (PMID 37736772, 2023). "In inflammatory diseases, OSM is strongly overexpressed in lesional skin from patients with psoriasis, atopic dermatitis and necrotic angiodermatitis." (PMID 35682987, 2022). "Then, we verified the results in psoriatic lesions and a psoriasis model in vitro by stimulating keratinocytes with IL-17A, IL-22, IL-1α, oncostatin M, and TNF-α (M5)." (PMID 35586566, 2022). "We then investigated the effect of curcumol on viability and proliferation of NHEK cells stimulated with a combination of proinflammatory cytokines characteristic for psoriasis (IL-1α, IL-17A, IL-22, oncostatin M, and TNF-α; mix M5)." (PMID 34314383, 2021). "MiR-766-3p was upregulated in both HaCaT cells treated with the psoriasis-related cytokine pool (IL-17A, IL-22, IL-1 alpha, oncostatin M, and TNF-alpha) and tissues." (PMID 34992498, 2021). "Our attempt to model skin inflammation showed that the combination of IL-17A, IL-22, IL-1α, OSM and TNFα (Mix M5) synergistically increases chemokine and antimicrobial-peptide expression, recapitulating some features of psoriasis." (PMID 25010647, 2014). "Furthermore, KCs stimulated by a combination of psoriasis-associated cytokines (TNF-α, IL-1A, IL-17A, IL-22, and oncostatin M) activate autophagic flux, which leads to recurrent psoriasis inflammation and increased skin barrier damage." (PMID 38606161, 2024). "Furthermore, we used a psoriasis-associated cytokine mixture (Pso Mix) (IL-17, TNF-α, IL-1α, OSM and IL-22) to stimulate primary KCs to mimic the psoriatic profile." (PMID 37497003, 2023). "In this study, we used HaCaT keratinocytes stimulated with M5, a cocktail of five inflammatory cytokines (TNF-α, oncostatin M, IL-1α, IL-17A, and IL-22), as an in vitro model of psoriasis with typical upregulation in the production of cytokines, chemokines, and antimicrobial peptides." (PMID 36555642, 2022). "Consistently, OSM is upregulated in mouse models of atopic dermatitis and psoriasis." (PMID 35812457, 2022). "The differential expression analysis identified several upregulated differentially expressed genes, including OSM, CXCL8, TREM1, CXCL1, CSF3R, BCL2A1 and CXCL2, in relapsed psoriasis skin compared with baseline lesional skin." (PMID 40181552, 2025). "Our data show that eCIRP expression was increased in the sera of psoriasis patients and imiquimod- (IMQ-) induced psoriatic mice and cells stimulated with proinflammatory cytokines (IL-1α, IL-17A, IL-22, oncostatin M, and TNF-α; mix M5)." (PMID 36110097, 2022).
psoriasis (continued). "The mixture of IL-17A, IL-22, oncostatin M, IL-1α, and TNF-α (M5) cytokines were used to simulate HaCaT keratinocytes to establish psoriatic keratinocyte model recapitulating some features of psoriasis in vitro." (PMID 33081840, 2020). "HaCaT cells were stimulated with a cocktail of five proinflammatory cytokines (M5), including IL-1α, IL-17A, IL-22, oncostatin M, and TNF-α that has been demonstrated as an in vitro model of psoriasis." (PMID 33149756, 2020). "Interestingly, the psoriasis-related inflammatory factors, including TNF-α, IL-17, IL-22, OSM, and IL-1α, promoted YAP1 up-regulation in keratinocytes, as indicated by increased YAP1 expression (& f)." (PMID 40108109, 2025). "This study aims to investigate the modulatory effects of IFN-γ and a proinflammatory cytokine mix (5MIX: IL-1α, IL-17A, IL-22, OsM, and TNF-α) on keratinocyte antigen-presenting capacities and their interactions with CD4+ lymphocytes, with a specific focus on their role in psoriasis pathogenesis." (PMID 39769151, 2024). "This study aimed to investigate the effects of IFN-γ and a cytokine mix (5MIX: IL-1α, IL-17A, IL-22, OsM, and TNF-α) on the antigen-presenting capabilities of keratinocytes, with a specific focus on immune-mediated dermatological conditions such as psoriasis (Ps)." (PMID 39769151, 2024). "Mixed cytokines, including IL-17A, IL-22, oncostatin M, IL-1α, and TNF-α (M5), are used to simulate HaCaT keratinocytes in vitro to establish a psoriatic keratinocyte model that generates some common phenotypic features of psoriasis." (PMID 34202301, 2021). "Mixed cytokines, including IL-17A, IL-22, oncostatin M, IL-1α, and TNF-α (M5), were used to simulate HaCaT keratinocytes to establish a psoriatic keratinocyte model that generates some phenotypic features in common psoriasis in vitro." (PMID 34202301, 2021). "A recent study found that histamine increased the expression of oncostatin M (OSM), a proinflammatory mediator involved in the pathogenesis of psoriasis and AD, in M1 macrophages via the activation of H1R, H2R and H4R, and in turn, OSM stimulated STAT3 phosphorylation in human keratinocytes." (PMID 34281281, 2021). "However, OSM is not required for psoriasis-like imiquimod-induced skin inflammation since genetic deletion of OSM did not affect the psoriatic phenotype in this setting." (PMID 35812457, 2022).
COVID-19 (22 papers, 2020 to 2025). A disease caused by infection with severe acute respiratory syndrome coronavirus 2. "Notably, the expression of genes encoding both TNFSF14 and OSM were down-regulated in the PBMCs from COVID-19 patients with severe disease in the analysis of CITE-seq data, which suggests a tissue origin for these cytokines." (PMID 32788292, 2020). "Our data determined the overexpression of OSM in COVID-19 patients, indicating the potential of OSM as the new target for COVID-19." (PMID 40300201, 2025). "Genes in the subnetwork of the CCL family showed different expression levels in the four groups of COVID-19 severity; in particular, OSM, CCL3, CCL7, and IL2RA showed higher expression in the high-severity COVID-19 samples." (PMID 40362649, 2025). "The expressions of CCNB1, CDK1, IRF4, MMP9 and OSM were significantly higher in COVID-19 samples compared with matched controls, while LTA was down-regulated in GSE171110 training dataset." (PMID 40300201, 2025). "Most recently, OSM was identified as one of the proteins that are found at high levels in the serum of COVID-19 intensive care unit (ICU) patients that correlated with disease severity, potentially pointing to a role for OSM in cytokine storm reactions during SARS-CoV-2 infections." (PMID 34376712, 2021). "Given the extensive role of OSM in inflammatory diseases, cancer, and the potential role of OSM in COVID-19, small molecule inhibitors of OSM could provide a much-needed tool for clinicians." (PMID 34376712, 2021). "Consistent with the bioinformatic analysis, CCNB1, CDK1, IRF4, MMP9 and OSM were significantly overexpressed, while LTA was de-expressed in COVID-19 patients compared with healthy controls." (PMID 40300201, 2025). "Interestingly, OSM also binds to the OSM receptor, leading to the recruitment of JAKs and subsequent signal transduction and activation of STAT3; thus, we can hypothesize that both CXCL9 and OSM participate in the upregulation of PD-L1 through the STAT activation pathway in COVID-19 patients." (PMID 36428847, 2022). "Further to these ligands, we also noted increased expression of EREG, OSM, B2M, as well as type II HLA molecules HLA-A, HLA-B, HLA-C, and HLA-E predominantly in CD4+ and CD8+ T cells and monocytes in patients with severe COVID-19." (PMID 33458558, 2021). "scRNA-seq results of COVID-19 find that changes of host factors including EN-RAGE, TNFSF14, oncostatin M, ANXA1, FPR1, and S100A8/9 are correlated with disease severity, revealing the possible pathogenesis of severe COVID-19 and potential host therapeutic targets." (PMID 35495713, 2022).
rheumatoid arthritis (21 papers, 2008 to 2025). A chronic, systemic autoimmune disorder characterized by inflammation in the synovial membranes and articular surfaces. "We focused on the cytokine oncostatin M (OSM), which is implicated in the pathogenesis of chronic inflammatory diseases such as inflammatory bowel disease, pulmonary fibrosis, rheumatoid arthritis, and cancer." (PMID 40638741, 2025). "In systemic sclerosis, rheumatoid arthritis or interstitial pulmonary fibrosis and other lung diseases associated with fibrosis, OSM has a profibrotic effect." (PMID 35682987, 2022). "Osm encodes Oncostatin M, a member of the IL-6 family that has proinflammatory functions and has been implicated in pathogenesis of rheumatoid arthritis and other inflammatory conditions." (PMID 26019272, 2015). "Oncostatin M (OSM) is a pro-inflammatory cytokine of the IL-6 family implicated in rheumatoid arthritis, lung fibrosis and skin disease." (PMID 21223559, 2011). "Oncostatin M (OSM) has been implicated in the pathophysiology of rheumatoid arthritis (RA) through its effect on inflammation and joint damage." (PMID 24286335, 2013). "OSM also plays an important role in fibrotic diseases such as systemic scleroderma, rheumatoid arthritis, interstitial pulmonary fibrosis as well as excessive scarring and can have a pro or an antifibrotic effect depending on the model." (PMID 35682987, 2022). "Oncostatin M (OSM) is a cytokine from the interleukin 6 (IL-6) family that has been shown to be elevated in synovial fluid of most rheumatoid arthritis (RA) patients, but only in a limited subset of OA patients." (PMID 33673583, 2021). "Recently, OSM has been considered to be a drug target for multiple inflammatory diseases, such as colitis and rheumatoid arthritis." (PMID 29871627, 2018). "This is in line with published data from fibroblast-like synoviocytes isolated from patients with rheumatoid arthritis and stimulated with recombinant OSM, in which OSM increased STAT1, STAT3 and STAT5 expression." (PMID 24710357, 2014). "Studies have explored Oncostatin M functions in cancer, bone metabolism, liver regeneration, and conditions with chronic inflammation including rheumatoid arthritis, lung and skin inflammatory disease, atherosclerosis, and cardiovascular disease." (PMID 24381786, 2013). "Oncostatin M has a pivotal role in rheumatoid arthritis (RA), where increased levels of OSM are found in the synovial fluid of RA patients." (PMID 22196363, 2011). "Anti-OSM has also been explored in clinical trials of humans with rheumatoid arthritis." (PMID 39123444, 2024). "Oncostatin M (OSM) is a pleiotropic, interleukin-6 family inflammatory cytokine that plays an important role in inflammatory diseases, including inflammatory bowel disease, rheumatoid arthritis, and cancer progression and metastasis." (PMID 34376712, 2021). "Interestingly, humanized antibodies against OSM are showing considerable promise in treating rheumatoid arthritis, where they inhibit leukocyte migration and reduce inflammation." (PMID 24659184, 2014). "Similarly, one group found that two IP injections, separated by two days, of Anti-OSM at 100 μg/mouse may be a promising therapeutic target for rheumatoid arthritis." (PMID 39123444, 2024). "The aims of this study were to do, comparative analysis of the levels of different cytokines such as LIF, TNF-alpha, IL-1, IL-6 and OSM, in the synovial fluid samples aspirated from 10 Rheumatoid arthritis (RA), 25 Osteoarthritis (OA) and 7 Mixed arthropathies (MA) patients." (PMID 21593968, 2008). "As a member of the IL-6 family, oncostatin M (OSM) has gradually received attention for its role and mechanism in the occurrence of rheumatoid arthritis (RA)." (PMID 38022540, 2023).
atherosclerosis (14 papers, 2013 to 2024). A disease characterized by the build-up of fatty material and calcium deposition in the arterial wall resulting in partial or complete occlusion of the arterial lumen. "Some previous in vitro research suggested that oncostatin M directly causes dyslipidemia and atherosclerosis, which contradicts our study." (PMID 38397957, 2024). "Attempts to contextualize these two molecules in the setting of atherosclerosis have also implicated the IL-6 class cytokine oncostatin M. However, given the multifactorial nature of atherosclerosis, a direct link between these three effectors is still being investigated." (PMID 38737892, 2024). "Oncostatin-M (OSM) is an IL-6 family inflammatory cytokine and plays a critical role in the development and progression of the underlying pathogenesis of atherosclerosis but the role of OSM in the context of plaque vulnerability and ECM remodeling has not been discussed in detail in the literature." (PMID 36856919, 2023). "Background and Aims: Oncostatin M (OSM) signaling is implicated in atherosclerosis, however the mechanism remains unclear." (PMID 33959646, 2021). "▪Initiation and progression of atherosclerosis and its impact on the expression of the proinflammatory cytokine oncostatin M." (PMID 39201414, 2024). "One cytokine, for which there is mounting evidence suggesting a role in atherosclerosis development is OSM." (PMID 33959646, 2021). "Oncostatin M (OSM) is an inflammatory cytokine of the interleukin-6 family which plays a crucial role in the pathogenesis of atherosclerosis." (PMID 34235245, 2021). "Previous studies indicate a role for Oncostatin M (OSM) in atherosclerosis and other chronic inflammatory diseases for which inhibitory antibodies are in development." (PMID 31461490, 2019). "The mildly pro-inflammatory state that is present in this animal model of hyperlipidemia makes it a suitable model to investigate the role of OSM in atherosclerosis prone conditions." (PMID 30273401, 2018). "OSM functions in atherosclerosis are likely complex on the basis of its ability to regulate endothelial cells, vascular SMC, and angiogenesis." (PMID 24381786, 2013). "Among the other inflammatory mediators, oncostatin-M (OSM), a pro-inflammatory cytokine, play an important role in the development and progression of atherosclerosis, however, the role of OSM in plaque vulnerability and extracellular matrix remodeling (ECM) is not well understood and studied." (PMID 36856919, 2023). "Moreover, murine studies showed that OSM receptor (OSMR)−/−ApoE−/− mice have reduced plaque size and improved plaque stability compared to their OSMR-expressing littermates, indicating that OSM drives atherosclerosis development." (PMID 33959646, 2021). "The aim of this study is to investigate whether OSM is involved in atherosclerosis development in a humanized mouse model and in man." (PMID 31461490, 2019). "The effects of gp130 cytokines on these cells (including oncostatin M-[OSM] and IL-6), some of which have been implicated in atherosclerosis, are currently unknown." (PMID 24307759, 2013). "OSM plays a role in atherosclerosis and its protective and detrimental effect is context-dependent, more research is warranted to investigate whether clinically targeting OSM and its downstream signaling directly has any effect on plaque vulnerability and ECM remodeling." (PMID 36856919, 2023). "Similarly, a role for Oncostatin M (OSM) in atherosclerosis has been suggested." (PMID 31461490, 2019). "Based on these findings and on the knowledge that endothelial cells are very high expressers of OSM receptors, we hypothesized that OSM may be involved in atherosclerosis development partially by inducing endothelial activation as a first step in the development of atherosclerosis." (PMID 30273401, 2018). "Therefore, silencing oncostatin M may be beneficial for treating atherosclerosis." (PMID 38397957, 2024).
atherosclerosis (continued). "This critical review discusses the role of mTOR, p27kip, and OSM in VSMC proliferation and differentiation followed by the therapeutic potential of targeting these mediators in atherosclerosis to attenuate plaque vulnerability." (PMID 38737892, 2024). "Further, the concept that OSM mediates plaque vulnerability is supported by the fact that OSM and TNF-α colocalize in atherosclerotic plaques and TNF- α plays a critical role in early as well as late stages of atherosclerosis." (PMID 36856919, 2023). "Finally, we focused on only three genes (OSM, OSMR and LIFR), while atherosclerosis is a multifactorial disease." (PMID 33959646, 2021). "Oncostatin M (OSM) is a relatively unknown cytokine that has been suggested to play a role in both endothelial activation and atherosclerosis." (PMID 30273401, 2018). "Collectively, these findings suggest that OSM may be involved in atherosclerosis development but so far this has never been studied." (PMID 31461490, 2019).
inflammatory bowel disease (14 papers, 2014 to 2025). A spectrum of small and large bowel inflammatory diseases of unknown etiology. "The interleukin-6 family cytokine, oncostatin-M (OSM) has been associated with response to tumor necrosis factor-α antagonists (anti-TNFs) in small cohorts of patients with inflammatory bowel disease (IBD)." (PMID 35075155, 2022). "OSM knockout mice with inflammatory bowel disease had reduced severity of overall pathology and disease features compared to wild-type mice." (PMID 39683503, 2024). "OSM expression was also increased in inflamed tissues of patients with inflammatory bowel disease, which was closely related to disease severity." (PMID 39683503, 2024). "Therapeutics targeting cytokines such as the oncostatin M (OSM)-mediated inflammation represent a potential strategy for the treatment of inflammatory bowel disease (IBD)." (PMID 32195265, 2020). "One such member, oncostatin M (OSM), has been associated with a wide variety of inflammatory disease states, such as in inflammatory bowel disease and arthritis." (PMID 29898744, 2018). "OSM protein expression was increased in colonic biopsies of patients with active inflammatory bowel disease (IBD)." (PMID 24710357, 2014). "OSM is a member of the interleukin-6 (IL-6) cytokine family and has been previously shown to drive intestinal inflammation in adults with inflammatory bowel disease, and a single nucleotide polymorphism in the OSM locus was associated with increased risk of IBD." (PMID 35410447, 2022). "In inflammatory bowel disease (IBD), OSM and its receptor (OSMR) are expressed in high levels in inflamed intestinal tissue, and levels are correlated with histopathological disease severity and CRP levels." (PMID 30621017, 2019). "Most recently, OSM has been shown to play a role in inflammatory bowel disease (IBD) with a study demonstrating heightened expression of OSM and its receptor in the inflamed IBD intestine, correlating with disease severity." (PMID 31555281, 2019).